H19 (H19 imprinted maternally expressed transcript)
Diseases named in the same sentence as H19 in open-access papers (continued):
Sharing a sentence is not in itself a finding about the gene and the disease.
lipid metabolism disorder (2 papers, 2023 to 2024). "HQC treatment alleviated GA lipid metabolism disorder and inflammation via the lncRNA H19/APN/PI3K/AKT cascade, implying the promising potential of HQC in the treatment of GA." (PMID 36994890, 2023). "HQC improved lipid metabolism disorder and inflammatory response of GA by regulating the lncRNA H19/APN/PI3K/AKT." (PMID 36994890, 2023).
liposarcoma (2 papers, 2020 to 2026). A usually painless malignant tumor that arises from adipose tissue. "The highest expression level was detected in the liposarcoma cell line SW872, whereas all other cell lines exhibited considerably lower or even undetectable levels of H19." (PMID 41521159, 2026).
lung disease (2 papers, 2016 to 2022). "The aim is to demonstrate its underlying mechanism in pulmonary diseases and to guide the basic research targeting H19 into clinical drug translation." (PMID 36188624, 2022). "It is not difficult to see from the table that there are currently three drugs targeting H19 to treat lung diseases, namely melatonin, Curcumenol and Ginsenoside Rb3." (PMID 36188624, 2022). "In recent years, people paid more attention to the roles of H19 in lung diseases, which expressed abnormally in various pathological process." (PMID 36188624, 2022). "The review aims to summarize the roles of H19 in pulmonary diseases to reveal the therapeutic target and the direction to improve treatment." (PMID 36188624, 2022). "Similarly, H19, a clinical marker with broad application prospects, is more and more concerned in lung diseases." (PMID 36188624, 2022). "Finally, we summarized the current studies on H19 in lung diseases to explain the potential therapeutic value of H19 in lung diseases." (PMID 36188624, 2022). "Therefore, we can also hypothesize whether drugs such as metformin and dihydroartemisinin may target H19 in lung disease." (PMID 36188624, 2022).
macroglossia (2 papers, 2015 to 2024). The presence of an excessively large tongue, which may be congenital or may develop as a result of a tumor or edema due to obstruction of lymphatic vessels, or it may occur in association with hyperpituitarism or acromegaly. "When birth, further studies displayed that the methylation and expression levels of H19/Igf2 in the NT-CON-M group were significantly higher than those in the NT-CON-N (cloned piglets without macroglossia), NT-TSA-N and IVF groups (P<0.05)." (PMID 25962071, 2015). "Encouragingly, no macroglossia occurred in the NT-TSA group, even the only one deceased cloned piglet, and the imprinting of H19/Igf2 were normal in the NT-TSA group, suggesting that TSA has a correcting effect on genomic imprinting." (PMID 25962071, 2015).
metastatic cancer (2 papers, 2020 to 2023). A carcinoma which has spread from the original site of growth to another anatomic site. "Meanwhile, compared with the adjacent tissues, Myc and H19 are highly expressed in metastatic cancer tissues, but the expression of H19-S has no significant change, indicating that the AT2 cells infiltrating metastatic cancer in clinical samples are rare." (PMID 37254190, 2023).
muscle atrophy (2 papers, 2023 to 2025). The loss of muscle tissue due to inactivity or disease. "In addition, H19, HOTAIR, MALAT1 and PVT1 are highly expressed in the kidneys of CKD patients and are associated with muscle atrophy but do not directly mediate the pathogenesis of muscle atrophy in CKD patients." (PMID 40034097, 2025).
muscular dystrophies (2 papers, 2021). "Recently, in muscular dystrophy (MD) patients, H19 was found to directly interact with dystrophin and inhibit E3-ligase-dependent polyubiquitination at Lys3584 for protein degradation." (PMID 34604357, 2021). "We previously reported that the lncRNA H19 regulates the poly-ubiquitination and protein stability of dystrophin (DMD) in muscular dystrophy." (PMID 34454586, 2021).
myelodysplastic syndrome (2 papers, 2020 to 2023). A clonal hematopoietic disorder characterized by dysplasia and ineffective hematopoiesis in one or more of the hematopoietic cell lines. "The lncRNAs LOC101928834, H19, WT1-AS, TCL6, LEF1-AS1, EPB41L4A-AS1, PVT1, GAS5 and ZFAS were found to be relevant to myelodysplastic syndrome (MDS) pathogenesis and outcome." (PMID 36607351, 2023).
osteonecrosis (2 papers, 2025 to 2026). A none disease characterized by death of bone tissue due to a lack of blood supply. "Second, H19’s therapeutic potential in animal models of steroid-induced osteonecrosis needs to be evaluated." (PMID 40259926, 2025).
ovarian endometriosis (2 papers, 2021 to 2025). A non-neoplastic disorder characterized by the growth of endometrial tissue in the ovaries. "Based on bioinformatics analysis of a ceRNA network, we identified the lncRNAs H19, GS1-358P8.4, and RP11-96D1.10 as being strongly associated with ovarian endometriosis." (PMID 33584822, 2021). "H19 and GS1-358P8.4 were identified as key ovarian endometriosis-related lncRNAs through topological feature analysis, and RP11-96D1.10 was identified using a random walk with restart algorithm." (PMID 33584822, 2021).
pancreatic neuroendocrine neoplasm (2 papers, 2021 to 2025). A neoplasm with neuroendocrine differentiation that arises from the pancreas. "In summary, these results demonstrated that H19 could promote pancreatic neuroendocrine neoplasm progression via the VGF-mediated PI3K/Akt/CREB pathway." (PMID 34977037, 2021). "H19 regulated the VGF expression level, which promoted pancreatic neuroendocrine neoplasm cell proliferation, migration and invasion." (PMID 34977037, 2021).
Peritoneal Fibrosis (2 papers, 2023 to 2025). Disorder characterized by a wide range of structural changes in PERITONEUM, resulting from fibrogenic or inflammatory processes. "H19 has recently been shown to be expressed in human and mouse mesothelium and to mediate peritoneal fibrosis." (PMID 40885718, 2025). "In the second study, tamoxifen reduced H19 levels by decreasing the ESR1-mediaed transcription of H19 in an experimental system of high glucose-induced peritoneal fibrosis." (PMID 40885718, 2025). "In this study, we clarified the mechanism of tamoxifen in alleviating high glucose-induced fibrosis by inhibiting ESR1 transcribing H19 in peritoneal fibrosis." (PMID 37697303, 2023). "To examine whether interfering with H19 could restrain high glucose-induced peritoneal fibrosis in mice, we injected PDF mixed with small interfering RNA targeting mouse H19 for treatment or siNC as a negative control." (PMID 37697303, 2023).
placental disease (2 papers, 2020 to 2022). "Previous studies reported a relationship between H19 and placental diseases." (PMID 35954272, 2022). "Several lncRNAs, such as H19 imprinted maternally expressed transcript (H19), X-inactive specific transcript (Xist) and SPRY4 intronic transcript 1 (SPRY4-IT1), were also characterized to be associated with trophoblast development and placental disease." (PMID 32268606, 2020).
postmenopausal osteoporosis (2 papers, 2020 to 2021). Metabolic disorder associated with fractures of the femoral neck, vertebrae, and distal forearm. "It has been found that H19 down-regulation modulated osteogenic differentiation of BMSCs from ovariectomized mouse, which suggested an important role of H19 in postmenopausal osteoporosis." (PMID 31918667, 2020). "Therefore, H19 is down-regulated in postmenopausal osteoporosis and promotes the up-regulation of miR-19b-3p." (PMID 34583640, 2021). "The data in our study indicated that estrogen inhibited miR-19b-3p, while elevated H19 expression in a dose-dependent manner, suggested a clear connection between estrogen and H19/miR-19b-3p, further confirm the biomarker potential of H19 and miR-19b-3p in postmenopausal osteoporosis." (PMID 31918667, 2020). "Moreover, we explored the potential correlation of lncRNA H19 and miR-19b-3p in postmenopausal osteoporosis." (PMID 31918667, 2020).
schizophrenia (2 papers, 2020 to 2022). A major psychotic disorder characterized by abnormalities in the perception or expression of reality. "Therefore, a possible mechanism for participation of HNF1A-AS1 in the pathobiology of schizophrenia is its role in induction of H19 expression." (PMID 33093650, 2020). "Examples include genes from the IGF2-H19 imprinted locus on chromosome 11p15, e.g., IGF2, H19, and miR483, and DLK1, DIO3, and miR134, which reside within the DLK1-DIO3 imprinted locus at 14q32 and whose misregulation is linked to schizophrenia and bipolar disorder." (PMID 35440587, 2022). "Next, we appraised the diagnostic power of transcript quantities of CHAST, CEBPA, DICER1-AS1, H19 and HNF1A-AS1 in distinguishing between patients with schizophrenia and controls through depicting ROC curves." (PMID 33093650, 2020). "We also appraised the diagnostic power of transcript quantities of CHAST, CEBPA, DICER1-AS1, H19 and HNF1A-AS1 in distinguishing between patients with schizophrenia and controls through depicting ROC curves." (PMID 33093650, 2020).
serous carcinoma (2 papers, 2018 to 2020). "Additionally, the involvement of H19 in platinum resistance was evidenced in a study of tissues obtained from 41 high-grade serous carcinoma patients treated with either cisplatin or carboplatin; the results revealed that H19 positively correlated with the early recurrence of OC." (PMID 32854207, 2020).
small cell lung carcinoma (2 papers, 2018 to 2021). Small cell lung cancer (SCLC) is a highly aggressive malignant neoplasm, accounting for 10-15% of lung cancer cases, characterized byrapid growth, and early metastasis. "Moreover, H19 promotes small cell lung cancer (SCLC) progression via sponging miR-140-5p." (PMID 34250088, 2021).
testicular tumors (2 papers, 2021). "That is the case of H19, which drives cisplatin resistance in testicular tumors, and whose inhibition could restore cancer cells sensitivity to these chemotherapeutics." (PMID 33767982, 2021).
thyroid tumor (2 papers, 2020 to 2025). A benign or malignant neoplasm affecting the thyroid gland. "Other important signatures are represented by the overexpression of the maternally imprinted lncRNA H19 as a consequence of its demethylation in placental tissues, and the overexpression of this lncRNA in thyroid tumors wherein can act as an oncogene." (PMID 33114343, 2020). "Finally, H19 is a characteristic lncRNA able to act as oncogene in several cancer types and exhibiting a higher expression both in thyroid tumors and in TC cells." (PMID 33114343, 2020). "Some lncRNAs, including H19 and ABHD11-AS1, are upregulated in thyroid tumors, which enhance EMT, proliferation, invasion, and angiogenesis, most often by acting as sponge molecules for microRNAs, or modulating key pathways, such as PI3K/Akt and ERK/MAPK." (PMID 41154428, 2025).
tongue cancer (2 papers, 2020 to 2022). A malignant neoplasm affecting the tongue. "This study aimed to analyze the regulation effect of ginsenoside Rd on H19 and miR-675-5p in tongue cancer." (PMID 36074434, 2022). "Ginsenoside Rd can also regulate the migration and invasion of tongue cancer cells through the H19/miR-675-5p/CDH1 axis." (PMID 36074434, 2022). "In this study, H19 expression was high in tongue cancer and promoted the invasion and migration of tongue cancer cells." (PMID 36074434, 2022). "Ginsenoside Rd inhibits tongue cancer cell migration and invasion via the H19/miR-675-5p/CDH1 axis." (PMID 36074434, 2022). "qPCR results showed that H19 expression was higher in tongue cancer tissues than in normal tissues." (PMID 36074434, 2022). "Overexpression of EZH2 and downregulation of H19 completely reversed H19 silencing-mediated inhibition of β-Catenin and GSK-3β activation in tongue cancer cells." (PMID 33052244, 2020). "Moreover, H19 and CDH1 may be potential markers of tongue cancer." (PMID 36074434, 2022).
Age-related cataract (1 paper, 2022). A type of cataract (opacification of the lens) that forms during the course of aging. "The expression of the lncRNA H19 was shown to regulate ageing in the endothelial HUVECS cells line, and to contribute to oxidative damage repair in age-related cataracts." (PMID 35205253, 2022).
alcohol abuse (1 paper, 2025). The use of alcoholic beverages to excess, either on individual occasions ("binge drinking") or as a regular practice. "Alcohol abuse can also alter methylation of the regulatory region of gene H19 and of genes DLK1 and GTL2 in the male gametes (40 men, alcohol consumers vs. controls)." (PMID 41153345, 2025).
alcoholic liver diseases (1 paper, 2025). A disorder caused by damage to the liver parenchyma due to alcohol consumption. "Through transcriptome sequencing of three groups of TM4 cells (CTRL, OGD/R, si-H19+OGD/R), we found that the TGF-β signaling pathway, mineral absorption, alcoholic liver disease, Hippo signaling pathway, and other pathways highly enriched in KEGG all pointed to the AKT signaling pathway." (PMID 40076761, 2025).
anaplastic cancer (1 paper, 2021). "Moreover, in this same study, targeting H19 inhibited tumor metastases by approximately eight-fold in comparison with that of controls, suggesting that H19 may be a potential target for molecular therapy in anaplastic cancer patients." (PMID 33543394, 2021).
ankylosis (1 paper, 2023). Fixation and immobility of a joint. "We found a highly significant correlation between the level of H19 expression in AS patients and new bone formation, or ankylosis, on their MRIs." (PMID 37373903, 2023).
arteriosclerosis obliterans (1 paper, 2019). Common occlusive arterial disease which is caused by atherosclerosis. "Reports have documented a high expression H19 in patients with AS, where H19 inhibits vascular endothelial cell apoptosis in arteriosclerosis obliterans through regulation of the mitogen-activated protein kinase/nuclear factor kappa-B signaling pathway." (PMID 31757932, 2019).
arthropathy (1 paper, 2023). Any disorder of the joints. "To test this hypothesis, we first investigated the expression of H19, Neat1 lncRNAs and their target genes in an arthropathy model of haemophilia mice." (PMID 37183540, 2023).
Autoimmunity (1 paper, 2024). The occurrence of an immune reaction against the organism's own cells or tissues. "In systemic lupus erythematosus (SLE), lncRNA H19 is significantly upregulated and inhibits the proliferation of Treg cells and promotes the conversion of Treg cells to Tfh cells through the direct inhibition of IL-2 production, which results in immune dysregulation and exacerbates autoimmunity." (PMID 38715092, 2024).
benign pancreatic tumours (1 paper, 2016). "And H19, HOTAIR, HOTTIP, MALAT1, and PVT1 levels did not significantly differ between NPT and benign pancreatic tumours (BPT) tissues (p values were 0.522, 0.759, 0.200, 0.631, and 1.000, respectively)." (PMID 27028998, 2016).
bipolar disorder (1 paper, 2022). A disorder of the brain that causes unusual shifts in mood, energy, activity levels and the ability to carry out day-to-day tasks. "It was also suggested that an effective treatment of lithium for bipolar disorder could be partially explained by reduced DNA methylation at the IGF2/H19 imprinting control region in mouse embryonic and neural stem cells." (PMID 35178127, 2022).
Bovine mastitis (1 paper, 2017). INFLAMMATION of the UDDER in cows. "To investigate whether H19 mediates the process of bovine mastitis, we first examined the expression of H19 in normal and inflammatory bovine mammary tissue." (PMID 29062612, 2017).
brachydactyly (1 paper, 2012). A disease characterized by the presence of brachydactyly, including syndromic and non-syndromic forms. "Accordingly, we speculate that in our patient a change in the methylation pattern of ZAC1 modifies the expression of H19 and/or IGF2 and gives rise to BWS phenotype, and perhaps even to the brachydactyly, because such a gene is highly expressed in chondrogenic tissue." (PMID 22974175, 2012).
cataract (1 paper, 2022). Partial or complete opacity of the crystalline lens of one or both eyes that decreases visual acuity and eventually results in blindness. "On Postnatal day 21 (P21), H19 (-/-) mice exhibited a delayed fusion of anterior sutures with cortical cataracts at the anterior polar regions, consistent with findings observed in semi-in vivo cultured mouse whole lenses with H19 forcibly silenced." (PMID 36010635, 2022). "Furthermore, we explored possible downstream mechanisms responsible for its functions, highlighting the potential role of the H19/miR-675-3p/SMAD4 axis in fibrotic cataracts." (PMID 36010635, 2022). "Thus, H19 could be a potential therapeutic option for fibrotic cataracts." (PMID 36010635, 2022). "At the same time, the downregulation of lncRNA H19 might aid in the EMT processes and accelerate the development of lens opacities." (PMID 36010635, 2022).
celiac disease (1 paper, 2019). An autoimmune genetic disorder with an unknown pattern of inheritance that primarily affects the digestive tract. "Third, we corrected the observed methylation degree based on the estimated calibration curves in two specific target regions (KCNQ1OT1 and H19/IGF2) important for their BWS clinical diagnostic value and in three target genes that have been associated with susceptibility to celiac disease." (PMID 31049595, 2019).
childhood leukemia (1 paper, 2021). An acute or chronic leukemia that occurs during childhood. "Our results indicate that H19 SNP rs2839698, but not rs217727, may serve as a novel susceptibility marker for childhood leukemia." (PMID 33800276, 2021).
cholelithiasis (1 paper, 2023). The presence of crystallized deposits forming in the gallbladder or biliary tree, primarily composed of cholesterol, bilirubin, and bile. "Cholelithiasis is associated with a higher H19 RNA expression." (PMID 37189829, 2023). "In the literature, there is a lack of information about the association between H19 and cholelithiasis, so this result is a novel finding." (PMID 37189829, 2023). "Patients with cholelithiasis had higher H19 expressions compared to patients without cholelithiasis and the controls." (PMID 37189829, 2023). "Moreover, patients with the co-occurrence of cholelithiasis had higher H19 expressions in comparison to patients without cholelithiasis and the controls." (PMID 37189829, 2023).
chronic heart failure (1 paper, 2017). "Another interesting finding in our study is that plasma H19 is increased in CAD patients with chronic heart failure (CHF)." (PMID 28790415, 2017).
chronic hepatitis (1 paper, 2024). An active inflammatory process affecting the liver for more than six months. "miR-675 is derived from the first exon of H19, and it was shown that H19 and miR-675 were upregulated in HBV-induced chronic hepatitis with the subsequent downregulation of miR-675 target PPARα with associated activation of Akt/mTOR signaling and perturbation of energy metabolism." (PMID 38203767, 2024).
clear cell sarcomas of the kidney (1 paper, 2023). "In a group of 30 cases of clear cell sarcomas of the kidney, 43% had IGF2 overexpressed considered IGF2 LOI, with retention of normal H19 expression." (PMID 37686532, 2023).
cocaine dependence (1 paper, 2016). A psychologically and socially impaired state, with or without physiological changes, that develops as a result of using cocaine and which leads to compulsive behaviors to acquire the substance. "Smokers had dramatically elevated H19 expression in airway epithelium; demethylation of H19 was correlated to chronic alcohol use in men; and many LncRNAs mediated cocaine-induced neural plasticity in the NAc and conferred risk for cocaine dependence." (PMID 27827986, 2016).
colitis (1 paper, 2024). Inflammation of the colon. "A study of the lncRNA H19 in intestinal epithelial cells in mice with DSS colitis concluded that H19 is an lncRNA involved in an inflammatory pathway linking IL22 to cell growth regulation which plays a role in intestinal epithelial regeneration under inflammatory conditions." (PMID 39201494, 2024).